MALAT1 (metastasis associated lung adenocarcinoma transcript 1)
Diseases named in the same sentence as MALAT1 in open-access papers (continued):
Sharing a sentence is not in itself a finding about the gene and the disease.
bladder cancer (continued). "Therefore, high MALAT1 expression can serve as an independent prognostic factor for OS of bladder cancer patients and can be considered as a potential therapeutic target of bladder cancer." (PMID 29899709, 2018). "The combination of three lncRNAs (MALAT1, PCAT-1, and SPRY4-IT1) had an area under the ROC curve (AUC) of 0.854 for bladder cancer diagnosis, which was significantly higher than that for urine cytology (0.619)." (PMID 37592177, 2023). "In bladder cancer, FTO accelerates tumorigenesis by removing m6A modifications and activating the MALAT1/miR-384/MAL2 cascade in MALAT1 mRNA." (PMID 37007161, 2023). "Exosomal MALAT1, PCAT-1 and PTENP1 have been found in many studies focused on the link between exosomes and bladder cancer, indicating these three molecules participate in the progression of bladder cancer in depth." (PMID 37805491, 2023). "Moreover, we found that FTO silencing in bladder cancer cells could significantly (p < 0.001) upregulate, by 1.5‐fold, the relative m6A level of MALAT1 5′‐End, whereas the overexpression of FTO could significantly (p < 0.001) decrease, by 24.3%, the relative m6A level of MALAT1 5′‐End." (PMID 33634966, 2021). "Zhan and et.al developed a urinary exosome-derived lncRNA panel (MALAT1, PCAT-1 and SPRY4-IT1) for diagnosis and recurrence prediction of bladder cancer in a cohort consist of 368 urine samples." (PMID 34861847, 2021). "FTO, MALAT1, miR‐384, and MAL2 are all clinically relevant biomarkers in bladder cancer, among which the expression of FTO influences the prognosis of bladder cancer patients." (PMID 33634966, 2021). "Similar to MALAT1, UCA1 was also reported to induce increase of the migratory and invasive abilities of bladder cancer cells by inducing EMT." (PMID 30813594, 2019). "They found a significantly higher expression of LINC00355, UCA1-203, and MALAT1 and a decreased UCA1-201 expression in bladder cancer patients compared to the other two groups." (PMID 35582278, 2019). "Of these, XIST, H19, MALAT1, MEG3 play a role in tumor proliferation, suppression, and metastasis of bladder cancer." (PMID 31379598, 2019). "Up to now, it was reported that some lncRNAs was aberrantly expressed in bladder cancer, such as HULC, MALAT1, and SNHG16." (PMID 29899709, 2018). "MALAT-1 is induced by TGF-β and plays a critical role during the promotion of EMT by TGF-β in bladder cancer cells." (PMID 29701689, 2018). "The expression of SNHG16, MALAT1, and UCA1 were up-regulated in bladder cancer tissue, while the expression of YRNA1, YRNA3, YRNA4, YRNA5, and MEG3 were down-regulated." (PMID 29899709, 2018). "Another lncRNA, MALAT-1, is induced by TGF-β and plays a critical role during the promotion of EMT by TGF-β in bladder cancer cells." (PMID 28430163, 2017). "Currently, numerous lncRNAs such as lncRNA-ATB and MALAT1 have been reported to be involved in the EMT process in liver cancer and bladder cancer, respectively." (PMID 28697764, 2017). "A recent study showed that the MALAT1 expression level was upregulated and promoted the activity of the PRC2 complex by interacting with the SUZ12 protein in bladder cancer." (PMID 28412742, 2017). "More researches suggested that upregulated MALAT1 can induce an epithelial-to-mesenchymal transition (EMT) and bladder cancer cell migration and promote brain metastasis." (PMID 28253859, 2017). "In bladder cancer, TGF-β1 induces MALAT1 expression, whereas silencing of endogenous MALAT1 and its binding partner, SUZ12, suppresses TGF-β1-induced EMT." (PMID 26989421, 2016). "In addition, a moderate significant correlation of MEG3, SNHG16 and MALAT1 between bladder cancer tissues and paired serum samples was also observed, which provides the strong evidence that BC-related lncRNAs could be released into the circulation and enriched in serum." (PMID 27793008, 2016).
bladder cancer (continued). "It has recently been demonstrated that MALAT-1 is induced by TGF-β in bladder cancer cells and its level is highly upregulated in bladder cancer specimens." (PMID 25428918, 2014). "Similarly, FTO-mediated m6A removal in MALAT1 mRNAs activated the MALAT1/miR-384/MAL2 cascade, leading to the development of bladder cancer." (PMID 38556586, 2024). "In bladder cancer, the expression of MALAT1 is up-regulated, and there is a negative correlation between the expression of MALAT1 and E-cadherin (E-cadherin)." (PMID 34026626, 2021). "Hsa-miR-125b can also inhibit the development of bladder cancer by inhibiting SIRT7 and MALAT1, and has additionally been found to play an essential role in the progression of oral squamous cell cancer (OSCC), as well as the target genes and transcription factors associated with hsa-miR-125b." (PMID 34315491, 2021). "MALAT1 and MAL2 interact with miR‐384 for regulating tumor growth of bladder cancer." (PMID 33634966, 2021). "The sensitivity of MALAT1, SNHG16 and UCA1 is 0.567, 0.642, 0.83; the specificity of MALAT1, SNHG16 and UCA1 is 0.675, 0.650, 0.86; the ROC curve AUC of MALAT1, SNHG16 and UCA1 used for bladder cancer is 0.635, 0.679, 0.86." (PMID 34422802, 2021). "The data suggest that MALAT1 may act as a RNA sponge to interact with miR‐384 and further modulation MAL2 expression and promote bladder cancer proliferation." (PMID 33634966, 2021). "MALAT1 also bound to SUZ12, thus promoting bladder cancer metastasis." (PMID 32393270, 2020). "For example, lncRNAs MALAT1, SUMO1P3, and CCAT2 have been reported to promote cell proliferation and suppress cell apoptosis in bladder cancer." (PMID 33537343, 2020). "Recent reports have indicated that MALAT1 directly binds to miR‐125b and regulates SIRT7 expression in bladder cancer 17; we investigated whether MALAT1 has similar inhibitory effects on miR‐125b levels in MM cells." (PMID 29214735, 2018). "MALAT1 is also upregulated in bladder cancer tissues relative to matched non-cancerous tissue samples." (PMID 27686732, 2016). "One study demonstrates previously that MALAT1 associates with PRC2 by interacting with SUZ12 but not EZH2 and that inhibition of MALAT1 decreases the binding of SUZ12 to the E-cadherin gene promoter in bladder cancer." (PMID 26516927, 2015). "Recent studies indicate that MALAT1 enhances the activity of the PRC2 complex in bladder cancer by interacting with the subunit SUZ12 but not the subunit EZH2 in PRC2." (PMID 26516927, 2015). "In addition, increased expression of MALAT-1 was also found to activate the Wnt pathway to promote EMT and human bladder cancer cell metastasis." (PMID 26932376, 2014). "Overall, in bladder cancer cells, knockdown of FTO significantly (p < 0.001) decreased the relative expression level and half‐life of MALAT1 mRNA, whereas FTO overexpression significantly increased, by 2.2‐fold, the relative expression level and half‐life of MALAT1 mRNA." (PMID 33634966, 2021). "We demonstrate that the mechanism underlying the oncogenic effect of FTO is based on its capability of MALAT1 demethylation and the regulatory functions on the MALAT/miR‐384/MAL2 axis, which are three of the crucial molecular biomarkers clinically relevant to bladder cancer." (PMID 33634966, 2021). "A panel of 96 target lncRNAs was used as a probe, some of which have been previously demonstrated to be involved in the development of bladder cancer or other tumors (UCA1, MALAT1, H19, and HOTAIR), while others have not yet been characterized." (PMID 38846969, 2024).
diabetes (105 papers, 2014 to 2025). "MALAT1 can potentially serve as a new biomarker and therapeutic target for the treatment of complications associated with diabetes mellitus." (PMID 39944202, 2025). "In the second model, after adjusting for age, sex, duration of diabetes and HbA1c, Oment-1 and MALAT1 were still significantly associated with the presence of CHD." (PMID 40350526, 2025). "In the context of diabetes,MALAT1 has been linked to beta-cell dysfunction via inhibitionof pancreatic and duodenal homeobox 1 (PDX-1)expression, which leads to reduced H3 histone acetylation." (PMID 41123190, 2025). "Overexpression of MALAT1 indicates an important pathogenetic mechanism of microvascular dysfunction associated with diabetes – hyperproliferation of endothelial cells through p38MAPK signaling." (PMID 39944202, 2025). "Among the aberrantly expressed LncRNAs in diabetes, metastasis-associated lung adenocarcinoma transcript 1 (MALAT1), a highly conserved LncRNA, is upregulated in diabetes, and it is shown to regulate oxidative stress–mitochondrial dysfunction." (PMID 40650203, 2025). "In general, elevated levels of MALAT1 expression in various complications associated with diabetes mellitus, as well as therapeutic effects on MALAT1 with synthetic oligonucleotides and siRNAs, define MALAT1 as a therapeutic target and potential biomarker." (PMID 39944202, 2025). "The results showed the diabetic peripheral neuropathy, high levels of AGEs, FBG and 2hPG, high expression of lncRNA MALAT1, low expression of miR-199b and long course of diabetes are independent risk factors for DHI (all P<0.05)." (PMID 41001679, 2025). "The results of this study showed that diabetic peripheral neuropathy, AGEs level, FBG and 2hPG level, high expression of LncRNA MALAT1, low expression of miR-199b and long course of diabetes were independent risk factors for DHI." (PMID 41001679, 2025). "MALAT1, a nuclear genome-encoded RNA, is also translocated to the mitochondria, and its mitochondrial levels are significantly increased in diabetes, resulting in damage to mitochondrial structural and functional integrity." (PMID 40650203, 2025). "Though most of the disease entities related to MALAT1 are associated with different kinds of cancers, it is also discussed in other disorders, such as liver fibrosis or diabetes." (PMID 38674413, 2024). "For example, MALAT1 up-regulation is an important pathogenic mechanism of diabetes-induced microvascular dysfunction." (PMID 37322431, 2023). "Highly conserved lncRNA MALAT1 plays a key role in diabetes-associated complications, including diabetic retinopathy (DR)." (PMID 36297381, 2022). "Metastasis-associated lung adenocarcinoma transcript 1 (MALAT1) plays a crucial role in the pathophysiological process associated with diabetes-related complications." (PMID 35163020, 2022). "LncRNAs participate in the progression of vascular disease and MALAT1 plays a crucial role in the pathophysiological process associated with diabetes-related complications." (PMID 35163020, 2022). "The lncRNA MALAT1 has been reported to be associated with diabetes-induced microvascular dysfunction, activate p38/MAPK signaling and regulate retinal endothelial cell function under diabetic condition." (PMID 34796177, 2021). "MALAT1 is among well studied and highly conserved lncRNAs, linked to a variety of pathological processes including various malignancies and diabetes-related complications." (PMID 35058920, 2021). "As regards the clinicopathological features, we observed a significant association between MALAT1 and comorbidity with diabetes mellitus." (PMID 33670447, 2021). "A significant number of studies have directly implicated MALAT1 in development of diabetes and insulin signaling." (PMID 32503170, 2020). "Previous studies have indicated a higher expression of MALAT1 in different models of diabetes and NAFLD, which was associated with oxidative stress induction and inflammatory factor production." (PMID 32368256, 2020).
diabetes (continued). "One of the most common intergenic lncRNAs, named MALAT1, which is located on chromosome 11q13.1 and 7 kb in size, has been functionally identified and characterized in ED-associated diabetes." (PMID 34968230, 2019). "lncRNA MALAT1 has been shown to play a pathogenic role in diabetes-induced endothelial cell dysfunction and its inhibition was found to inhibit retinal endothelial cell proliferation, migration, and tube formation and ameliorate DR." (PMID 29915562, 2018). "MALAT1 upregulation represents a critical pathogenic mechanism for diabetes-induced microvascular dysfunction." (PMID 25356875, 2014). "Diabetes-induced MALAT1 upregulation represents an important pathogenic mechanism for diabetic microvascular complication." (PMID 25356875, 2014). "Recent studies have also shown that metastasis-associated lung adenocarcinoma transcript 1 (MALAT1) plays a crucial role in various pathophysiological processes, including the progression of diabetes and diabetic-related complications, by influencing gene transcription." (PMID 39944202, 2025). "Genetic variants within non-coding RNA loci further can modulate disease susceptibility, for example MALAT1 rs619586 exerted protective effects against Type 1 Diabetes Mellitus (T1DM), whereas miR-146a rs57095329 variants increased disease risk and metabolic impairment in pediatric patients." (PMID 41226804, 2025). "The p38/MAPK-signaling pathway may be a key bridge between MALAT1 and diabetes-associated intervertebral disc degeneration." (PMID 39502508, 2024). "In addition, MALAT1 was also reported to be involved in diabetes-associated intervertebral disc degeneration, which is a diabetes-associated complication." (PMID 39502508, 2024). "Thus, future research should combine more molecular biology and cell biology techniques to further elucidate the role of the MALAT1/miR-382-3p/BDNF signaling pathway in diabetes-associated cognitive impairment." (PMID 37740187, 2023). "The expression of lncRNA–MALAT1 was significantly upregulated in the retina of diabetic rats and diabetic mouse models, and MALAT1 knockdown improved DR and reversed the severe pericyte loss caused by diabetes." (PMID 36551201, 2022). "Our study indicates that macrophage-derived exosomes containing MALAT1 may serve as a novel cell-free approach for the treatment of vascular disease caused by diabetes mellitus." (PMID 35163020, 2022). "LncRNA MALAT1 is thought to be intimately linked to pyroptosis in diabetes complications." (PMID 35087834, 2021). "Additionally, lncRNA MALAT1 can also target Saa3 directly or indirectly to cause many diseases such as inflammation, diabetes and septic cardiomyocytes." (PMID 32969837, 2020). "Many lncRNAs have been associated to T2D and diabetes complications such as MALAT1, that correlates to cardiomyopathy, or circRNAs targeting hsa-miR-6760-3p, hsa-miR-761, hsa-miR-6728-3p, hsa-miR-5693, hsa-miR-298, and hsa-miR-367-5p which have been correlated to depression in T2D patient." (PMID 31191327, 2019). "Diabetes leads to a severe pericytes loss and aggravated capillary degeneration, whereas MALAT1 knockdown could reverse this trend." (PMID 25356875, 2014). "Given that Oment-1 has anti-inflammatory and antioxidative effects, whereas MALAT1 is associated with proinflammatory activity, our findings suggest a potential regulatory network involving adipokines (e.g., Oment-1) and lncRNAs (e.g., MALAT1) in the pathogenesis of diabetic vascular complications." (PMID 40350526, 2025). "LncRNA metastasis-associated lung adenocarcinoma transcript 1 (MALAT1) which is related to inflammation, oxidative stress, and angiogenesis, is widely expressed in a variety of tissues in vivo and has been confirmed to play a significant role in the complications of diabetes." (PMID 38439031, 2024).
diabetes (continued). "AstraZeneca developed a Glp-1-conjugated ASO targeting lncRNA metastasis-associated lung adenocarcinoma transcript 1 (MALAT1), to achieve pancreatic β cell-specific oligonucleotide uptake for treating diabetes, whose application could be transferred to improve dysregulated liver metabolism in NASH." (PMID 38665220, 2024). "A better understanding of the detailed mechanisms associated with the therapeutic targets of MALAT1 under hyperglycemic conditions will provide new insights into the therapeutic development of vascular disease that is frequently encountered in patients suffering from diabetes mellitus." (PMID 35163020, 2022). "lncRNA metastasis‐associated lung adenocarcinoma transcript 1 (MALAT1) was associated with diabetes‐induced microvascular dysfunction, as up‐regulation of MALAT1 could activate p38/MAPK signalling and regulate retinal endothelial cell function under diabetic condition." (PMID 28643459, 2017). "Several LncRNAs are aberrantly expressed in diabetes, and among them, MALAT1 is upregulated in the retina, altering the expression of the genes associated with inflammation." (PMID 40650203, 2025). "We have previously shown that, in diabetes, MALAT1 is upregulated in the retina and its capillary cells, Mfn2 promoter DNA is hypermethylated, and mitochondrial fission is increased." (PMID 40650203, 2025). "MALAT1, one of the highly conserved LncRNAs, is upregulated in the retina in diabetes, which is shown to increase oxidative stress via regulating the master transcriptional factor Nrf2 and inflammatory mediators." (PMID 40650203, 2025). "In conclusion, the upregulation of MALAT1 in diabetes facilitates Mfn2 promoter DNA hypermethylation in retinal vascular and nonvascular cells, leading to its suppression and the accumulation of the fragmented/damaged mitochondria." (PMID 40650203, 2025). "Metastasis-associated lung adenocarcinoma transcript 1(MALAT1) is associated with vascular calcification and diabetes-related complications." (PMID 41440015, 2025). "LncRNAs can regulate gene expression by epigenetic modifications, and Mfn2 promoter DNA is hypermethylated in diabetes; the role of MALAT1 in Mfn2 DNA methylation was evaluated." (PMID 40650203, 2025). "As a long non-coding RNA (lncRNA), Malat1 has been identified in many pathological processes with immunological components, including several types of cancer and diabetes." (PMID 41134910, 2025). "Hypoxia—which is a central pathophysiological phenomenon in diabetes-targeted organs—induces transactivation of the MALAT1 promoter through enhanced activity of the hypoxia-inducible factor-1α (HIF-1α) in vitro." (PMID 38202299, 2024). "Our results demonstrated that the expression level of lncRNA MALAT1 in the LEAD group was significantly greater than that in the simple diabetes group, suggesting that MALAT1 plays a role in diabetic lower limb atherosclerotic disease." (PMID 38439031, 2024). "Previous studies have focused on the relationship between MALAT1 and microvascular and coronary heart disease in diabetes." (PMID 38439031, 2024). "It has been reported that MALAT1 was up‐regulated in hearts of diabetic rats, and knockdown of MALAT1 significantly attenuated inflammation and cardiomyocyte apoptosis and improved diabetes‐induced cardiac dysfunction." (PMID 37395157, 2023). "We have studied the ncRNAs ZFAS1, MALAT1, miR-9, miR-146a and miR-200b in the context of diabetes and hyperglycemia-induced EndMT." (PMID 37924123, 2023). "MALAT-1 is involved in oxidative damage and complications related to diabetes such as diabetic nephropathy, vascular complications and diabetic retinopathy, and diabetic cataract." (PMID 37168992, 2023). "It is commonly used but not limited to the treatment of heart conditions, diabetes, obesity, and certain cancers where they have been found to dysregulate miR-16, miR-145, MALAT-1, miR-155, miR-146a, miR-197, lncRNA SNHG7 and miR-223." (PMID 37168992, 2023).